COL1A1 (collagen type I alpha 1 chain)
Diseases named in the same sentence as COL1A1 in open-access papers (continued):
Sharing a sentence is not in itself a finding about the gene and the disease.
liver fibrosis (continued). "Repeated administration of CCl4 caused a gradual elevation of Col1a1 mRNA expression and protein levels of COL1A1 and α-SMA, confirming the progression of liver fibrosis." (PMID 35637968, 2022). "Since the formation of hepatic fibrosis is a complex process of multi-factor and multi-cell involvement, our findings also point to the possible involvement of VACN, COL1A1, COL1A2, LUM, and FBLN5 in the generation of fibrotic response from NAFL to NASH." (PMID 36329886, 2022). "α-SMA, COL1A1 and TGF-β1 are all crucial biomarkers for liver fibrosis, while their downregulation is a sign of liver fibrosis recovery." (PMID 36093813, 2022). "After knocking out TRPV1, CCl4-induced liver injury and hepatic fibrosis aggravated and TGF-β-induced α-SMA and COL1A1 protein expression and HSC proliferation were significantly enhanced." (PMID 35909891, 2022). "Animal experiments have shown that quercetin can ameliorate liver fibrosis by inhibiting HSCs activation and ECM formation and regulating COL1A1, COL3A1, MMP9, and TIMP1 mRNA expression levels." (PMID 35791909, 2022). "Longer-term observation revealed that liver fibrosis was significantly attenuated in PTEN/SCAPΔL;S1aTg mice compared with PTEN/SCAPΔL mice at 5 months of age and that Col1a1 mRNA expression was also significantly decreased." (PMID 35380992, 2022). "This induces the deactivation of CAFs, with the consequent reduction in the secretion of ECM components (COL1A1, COL1A2, and FN1) and liver fibrosis." (PMID 36443822, 2022). "To confirm the level of liver fibrosis, we measured the mRNA expression of fibrotic factors, including α-smooth muscle actin (α-SMA), collagen type 1 alpha 1 (Col1a1), and transforming growth factor-beta (TGF-β), in the livers of mice." (PMID 36501154, 2022). "We found that COL1A1, COL4A2, and α-SMA mRNA expressions were significantly increased in the liver of the model, while the transcription of such liver fibrosis-related genes was significantly inhibited by GFL." (PMID 36278176, 2022). "HSCs act as a prominent player in the process of liver fibrosis because of its ability to produce fibrogenic proteins, α-SMA and CoL1A1." (PMID 34676206, 2021). "The massive deposition of collagen type I alpha I (COL1A1) and collagen III in the interstitium is a sign of advanced hepatic fibrosis." (PMID 34820381, 2021). "Knockout of myeloid HIF1α inhibits the expression of PDGF, α-SMA and Col1A1 induced by BDL, and significantly mitigates the progression of liver fibrosis." (PMID 34853322, 2021). "Hepatic mRNA levels of the fibrosis markers, Timp1 and Col1a1, revealed the protective effect of clodronate against MCD diet-induced liver fibrosis." (PMID 33664289, 2021). "Many of these genes, including COL1A1, LOX, MMP14, TGFB3, TIMP1 and VCAN, are known markers for liver fibrosis." (PMID 34588551, 2021). "In line with the progressive damage, DEN potentiated hepatic fibrosis in rats fed the ATH diet compared to the CD feeding, as seen by the increase in the expression of Col1a1, Acta2, and Tgfβ, and Sirius red staining, as well as α-SMA." (PMID 34439245, 2021). "CAPN2, as a subtype of CAPN, played a crucial role in the expression of hepatic fibrosis markers, including COL3A1, COL1A1 and MAPK1." (PMID 33836021, 2021). "Liver inflammation and liver fibrosis, as assessed by serum ALT levels, hepatic Col1a1 gene expression, and hydroxyproline levels, were restored to the original level by day 7 after the diet switch." (PMID 34294714, 2021). "HSCs are a prominent driver of liver fibrosis as the activated HSCs promote collagen deposition in the extracellular matrix by producing profibrogenic genes (α-SMA and CoL1A1), both of which are considered as markers of HSC activation." (PMID 32873229, 2020). "Baicalin (extracted from Scutellaria baicalensis Georgi) and aqueous extract of Salvia miltiorrhiza Bunge show the anti-inflammatory action, further improve liver fibrosis by inhibition of α-SMA, Col1A1, and TGF-β1 production." (PMID 32477116, 2020).
liver fibrosis (continued). "An in vitro study showed that IL-17A enhances the expression of pro-fibrotic genes (e.g., ACTA2 and COL1A1) by hepatic stellate cells through JNK-dependent up-regulation of TGF-β receptor on these cells, providing a possible mechanism for liver fibrosis." (PMID 33013934, 2020). "In line with the histological analysis, results from the mRNA expression of pro-fibrotic genes (including Acta2, Col1a1, Col1a2, and Tgfb1) further demonstrated that prophylactic but not therapeutic administration of OCA were effective against liver fibrosis." (PMID 31932588, 2020). "The mRNA levels of collagen type 1 (Col1a1), connective tissue growth factor (CTGF), and tissue inhibitor of matrix metalloproteinase 1 (Timp1), which are indicators of liver fibrosis, were measured." (PMID 32316419, 2020). "PGRN significantly attenuated CCl4-induced hepatic fibrosis with a concomitant reduction in α-SMA-, Col1a1-, and F4/80 antigen-positive cells." (PMID 31591383, 2019). "miR-185 targeted SREBF1, and increased expression of COL1A1 and a-SMA genes that are hallmarks of liver fibrosis." (PMID 27677421, 2016). "In the context of fibrosis, inhibiting BRD4 with JQ1 inhibits both lung and liver fibrosis as well as HSC activation in murine models, including reducing TGF-β-mediated Col1A1 expression and extracellular matrix remodeling." (PMID 27990121, 2016). "Quantitative analysis revealed that miR-706 significantly decreased hydroxyproline content compared to control agomir, and greatly attenuated the severity of liver fibrosis, as demonstrated by α-SMA, Col1a1, Sirius red staining." (PMID 27876854, 2016). "Ten DEGs including PDGFra, PDGFrb, PDGFb, PDGFd, COL1A1, COL1A2, COL5A2, ITGA5, THBS1 and IL1R1, closely related to liver fibrosis, were chosen for the real-time qRT-PCR analysis." (PMID 26691002, 2015). "CD1d-knockout mice developed minimal hepatic fibrosis induced by administration of TAA, which was accompanied by reduction in collagen type I alpha 1 (COL1A1) and TIMP-1 expression." (PMID 25954568, 2015). "In one study, β-caryophyllene exhibited high scavenging activity against hydroxyl radicals and superoxide anions, which inhibited lipid peroxidation and suppressed expression of Col1a1 and TIMP-1 in CCl4-induced mouse liver fibrosis." (PMID 25897319, 2015). "HQD down-regulated the expressions of PDGFra, PDGFrb, PDGFb, PDGFd, COL1A1, COL1A2, COL5A2 and THBS1, and TGF-β and PDGF signaling pathways in the DMN-induced liver fibrosis in rats." (PMID 26691002, 2015). "Therefore, COL1A1 and COL1A2 are recognized as key molecular markers for MASLD fibrosis, and their expression levels can be used to assess hepatic fibrosis severity and predict therapeutic responses." (PMID 41306725, 2025). "To analyze the degree of liver fibrosis in these groups of mice, we performed immunoblotting for α‐SMA, THBS1, and CTGF as well as Sirius Red staining for collagen and immunohistochemistry (IHC) for COL1A1." (PMID 40548862, 2025). "Furthermore, in liver fibrosis models, CCL2 and other pro-inflammatory markers are elevated alongside COL1A1 overexpression, indicating a synergistic role in fibrosis." (PMID 40606673, 2025). "Quantification of liver collagen levels revealed that antibiotic treatment alone did not affect liver fibrosis but partially blocked 4-MU’s suppression of liver fibrogenesis, a pattern similar to Col1a1 expression." (PMID 40475534, 2025). "DHA, but not EPA, has been shown to attenuate Western diet-induced hepatic fibrosis, as evidenced by the decreased gene and protein expression of collagen type I alpha 1 chain (Col1A1) and improved histological outcomes." (PMID 40647314, 2025). "Additionally, mRNA levels of fibrosis markers, COL1A1 and TGFB1, were elevated during hepatic fibrosis, alongside an increase in CXCR6 expression." (PMID 40822973, 2025). "This alleviated liver fibrosis by reducing the levels of α-SMA, COL1A1, and inflammatory factors." (PMID 40611207, 2025).
liver fibrosis (continued). "Additionally, M2-BMDM-EV treatment markedly inhibited cell apoptosis and suppressed the expression of liver fibrosis markers, including α-SMA and collagen type I alpha 1 (Col1a1)." (PMID 40448016, 2025). "Our study revealed that AURKA expression increases with the progression of liver fibrosis and is positively correlated with ACTA2, a marker of activated HSCs, as well as the fibrogenic genes COL1A1 and TIMP1, based on publicly available gene expression datasets from liver fibrosis patients." (PMID 39834933, 2024). "LncRNA XIST has been found to be highly expressed in liver tissue of ALD patients and reduces miR-29b inhibition of COL1A1 and α-SMA by competitively binding to miR-29b, which in turn promotes collagen synthesis and HSC activation and exacerbates liver fibrosis." (PMID 39533619, 2024). "Interestingly, supplementation with DHBA failed to increase the level of ALT/AST, TNF-α/IL-6, or TGF-β1/α-SMA/COL1A1 in CCl4-challenged GPR81 KO mice, suggesting that the detrimental effects of DHBA on CCl4-induced liver fibrosis depend on GPR81." (PMID 38982366, 2024). "Studies using HSCs have shown that miR-33a was found to be correlated with the increased expression of type I collagen (Col1A1) and α-smooth muscle actin (αSMA) by transforming growth factor beta (TGFβ), suggesting its involvement in the progression of NAFLD to liver fibrosis." (PMID 37371692, 2023). "As expected from previous publications, WT (i.e., Ccne1f/f) mice developed pronounced liver fibrosis with excessive hepatic collagen deposition upon combined DEN/CCl4 treatment, which was accompanied by substantial induction of Col1a1 gene expression and upregulation of Acta2." (PMID 37620309, 2023). "Furthermore, liver fibrosis was suppressed in the samples of F4MKO mice assessed by Sirius Red staining, along with the downregulation of key genes of fibrosis (Acat2, Col1a1, Col1a2, Timp2, and Tgfβ)." (PMID 37770480, 2023). "In the context of liver fibrosis, the upregulation of TRPC6, TRPV3, TRPV4, and TRPM7 channels promotes the activation of HSCs and the production and accumulation of ECM components, including α-SMA and COL1A1." (PMID 37569884, 2023). "Importantly, Cdk2ΔHSC mice showed a significant reduction of hepatic fibrosis compared to WT controls as determined by Sirius Red staining of fibers and measurement of HSC activation markers Acta2 and Col1a1." (PMID 37620309, 2023). "However, the administration of pcDNA-LIN exacerbated BDL-induced hepatic fibrosis, as indicated by macroscopic examination, HE and Masson staining, IHC and WB of α-SMA and COL1A1." (PMID 36672150, 2023). "To determine how LPJZ-658 prevented hepatic fibrosis in NASH mice, we examined the expression of transforming growth factor-β (TGF-β), a master regulator of fibrogenesis, and targeted genes such as collagen 1 alpha 1 (Col1a1) in the liver." (PMID 37762300, 2023). "Liver fibrosis levels, indicated by Col1a1 and Acta2 expression, and hepatic collagen levels were not different." (PMID 37626991, 2023). "Lastly, although prolonged MCD diet feeding of mice housed at Tn increased the hepatic expression of Col1a1 (p=0.02) and Col1a2 (p=0.01), such induction did not yield robust histological differences in hepatic fibrosis at the conclusion of the study." (PMID 36875069, 2023). "COL1A1 (type I collagen), as the mainly ECM collagen, have a critical role in liver fibrosis." (PMID 35791909, 2022). "To further confirm the effect of TRPV1 on CCl4-induced hepatic fibrosis, we evaluated the effect of capsaicin-induced TRPV1 activation and TRPV1 KO on CCl4-induced hepatic fibrosis by measuring the protein expression of fibrosis markers, including α-SMA and COL1A1." (PMID 35909891, 2022). "Furthermore, it was observed that the levels of Acta2, Col1a1, Col3a1, Tnfa, Il6, and Il1β genes were significantly increased upon STAT3 overexpression, again suggesting that STAT3 mitigated liver fibrosis." (PMID 36588728, 2022).
liver fibrosis (continued). "According to the present study findings, RF can reduce liver fibrosis by altering TGF-β/Smad signaling by decreasing protein expression of Smad2/3 phosphorylation and Smad4 formation, which results in down-regulation of Col1A1 and α-SMA transcriptions." (PMID 35549741, 2022). "Many predicted targets such as TIMP1, MMP2, COL1A1, MMP7, and COL3A1 have been involved in liver fibrogenesis and could be potential therapeutic targets for liver fibrosis." (PMID 35791909, 2022). "Moreover, ADSC-EVs carrying miR-223-3p were experimentally confirmed to confer hepatoprotection in vitro, corresponding to reduced contents of TG and TC as well as the expression of liver fibrosis markers α-SMA, COL1A1 and TGF-β1." (PMID 36093813, 2022). "Furthermore, levels of liver transcripts of genes indicative of liver fibrosis, such as transforming growth factor beta 1 (TGFB1), actin alpha 2 (Acta2) (αSMA) and collagen type I alpha 1 (Col1a1), were measured." (PMID 35057565, 2022). "However, it has been reported that Ets-1 suppresses the production of ECM by down-regulating matrix related genes such as COL1A1 induced by TGF-β, and ultimately inhibit liver fibrosis." (PMID 34820381, 2021). "The mRNA levels of the fibrotic markers, Col1a1 and Timp1, were also elevated, but no significant signs of liver fibrosis were observed by Sirius-red staining of liver sections of WT and IKKβca;A20LKO mice." (PMID 34626855, 2021). "Similarly, as important fibrotic markers, α-SMA, TGF-β, COL1A1, and desmin expression was also inhibited by KXRG treatment, thus inhibiting hepatic fibrosis." (PMID 34422075, 2021). "The expression levels of DNA methyltransferases 3A (DNMT3A), ANRIL, α‐Smooth muscle actin (α‐SMA), Type I collagen (Col1A1), adenosine monophosphate‐activated protein kinase (AMPK) and p‐AMPK in rat and human liver fibrosis were detected by immunohistochemistry, qRT‐PCR and Western blotting." (PMID 31961061, 2020). "In addition, rottlerin treatment also suppressed TGFβ1-induced expression of ACTA2, COL1A1, COL1A2, and CCL2, the expression of which is greatly increased in HSCs of liver fibrosis patients." (PMID 32210801, 2020). "Additionally, roseotoxin B also reduced the expression level of liver fibrosis-related α-SMA, Col1A1 and Col3A1 in the PDGF-BB-activated CFSC-8B cells." (PMID 32541811, 2020). "Upregulation of TGFB1, TGFB2, COL1A1, and COL3A1 were found at W14 post-infection but in both infected and uninfected groups, suggesting that there may be alternative mechanisms for hepatic fibrosis in liver fluke-infected cattle." (PMID 31555289, 2019). "Moreover, the amelioration of hepatic fibrosis by FBR treatment was partly mediated by hepatic mRNA expression levels of fibrosis‐related genes including αSMA, TGFβ1, and Col1A1." (PMID 31660146, 2019). "Overall, this study greatly enriched the anti-COL1A1 SAR of the tricyclic matrinic derivatives and thus offered powerful information for further structure optimization, noting that compound 8a was chosen as an ideal anti-liver fibrosis lead." (PMID 31627430, 2019). "Additionally, expression of pro-fibrotic genes, including Acta2, Col1a1, and Tgfb1 was significantly higher the CDAA and CDAA + fructose groups in parallel with the differences in liver fibrosis and numbers of activated HSCs." (PMID 29983886, 2018). "The expression of COL1A1, AFP and ALB are correlated with progression of liver fibrosis." (PMID 30346985, 2018). "Furthermore, miR-185 targets SREBF1, and increases expression of COL1A1 and a-SMA genes that are involved in liver fibrosis." (PMID 27677421, 2016). "Furthermore, miR-185 targeted SREBF1 and increased expression of COL1A1 and a-SMA genes, which are hallmarks of liver fibrosis." (PMID 27677421, 2016). "Suppressing COL1A1 and COL1A2 expressions might decrease the activation of HSCs and eventually prevent liver fibrosis." (PMID 26691002, 2015).
liver fibrosis (continued). "The mRNAs of liver fibrosis factors, such as α-SMA, Col1a1, platelet-derived growth factor receptor (PDGFR)-β, TGF-β1, fibronectin (FN) 1, discoidin domain receptor (DDR) 2, and β1 integrin (ITGB1), were upregulated in the livers of MCDD-fed mice compared to MCCD-fed mice B." (PMID 22849305, 2012). "Consistent with prior studies, COL1A1 is the most abundant collagen in the ECM and is widely involved in pathological processes such as fibrosis, TME remodeling and tissue sclerosis, playing a critical role in diseases such as liver fibrosis and cancer metastasis." (PMID 41258075, 2025). "Similarly as in the CCl4 model, we have not observed differences in the degree of liver fibrosis, hydroxyproline content, aminotransferase activities and Col1a1/Acta2 between Cre+ and Cre-mice in the DDC model." (PMID 39529885, 2024). "Notably, CCl4-treated Il15ra–/– mice showed even less staining of COL1A1 and CD45+ cell infiltration compared to Il15–/– mice, clearly indicating that IL-15 signaling via IL-15Rα-dependent trans-presentation promotes liver fibrosis via promoting inflammatory cell recruitment." (PMID 38919611, 2024). "In mice, DPP4is decrease liver fibrosis; however, this was not recapitulated by genetically eliminating Dpp4 as Picrosirius red staining revealed a trend toward increased fibrosis, and expression of Col1a1 and Col3a1 was increased in Dpp4–/– mice." (PMID 36472923, 2023). "CCl4 injection resulted in liver fibrosis with a more pronounced effect in Parkin-/- mice, as shown by the hepatic mRNA levels of markers for hepatic stellate cell (HSC) activation and fibrosis (Col1a1, Acta22, and Mmp2) as well as Masson and Sirius red staining." (PMID 36658227, 2023). "This resulted in improved histology and decreased ALT, proinflammatory factor, and hepatic fibrosis gene mRNAs (Il1, Il6, Timp1 and Tgfb) and proteins expression (IL1β, IL6, α-smooth muscle actin (αSMA), COL1A1, TGFβ and TIMP1) revealing that P. distasonis could improve TAA-induced hepatic fibrosis." (PMID 37005411, 2023). "Moreover, hepatic GR may also be important in preventing the development of liver fibrosis, manifested by hepatic induction of PAI-1 and Col1a1 in the GR KO mice." (PMID 35614477, 2022). "Moreover, atorvastatin did not mitigate liver fibrosis as evaluated by Sirius red liver staining and by the mRNA expression of fibrotic markers such as αSMA, Col1a1, and Tgfβ1." (PMID 34208774, 2021). "In addition, administration of sesamin suppressed liver mRNA expression of α-smooth muscle actin (αSMA) and collagen α-1(I) (Col1a1), which are liver fibrosis markers, in the CCl4-treated WT mice, but not in the ANX A1-null mice." (PMID 32133417, 2020). "Taking COL1A1 promotor as the biomarker, a luciferase screening cell model based on the elevation effect of TGF-β1 upon the expression of COL1A1 promoter was established earlier in our group, and successfully applied to the screening and evaluation of anti-hepatic fibrosis drug candidates." (PMID 33121156, 2020). "At 5 weeks of age, the expression of the extracellular matrix genes Col1a1 (12842) and Epcam (17075) were upregulated in DKO livers, and as a consequence DKO liver displayed fibrosis as detected by Azan staining; chronic hepatitis and cholestasis are known to lead to liver fibrosis." (PMID 26222436, 2015). "In addition, the transcript levels of liver fibrosis-related genes such as collagen type I alpha 1 chain (Col1a1) and collagen type III alpha 1 chain (Col3a1) were significantly downregulated by YC-1102, indicating that YC-1102 could inhibit NASH-induced liver fibrosis." (PMID 38921022, 2024). "Likewise, we could not detect lower gene expression of hepatic collagen I (Col1a1 and Col1a2) or other liver fibrosis-promoting genes such as Lox25 or Timp126 in any of the dose groups evaluated." (PMID 37816736, 2023).